SYNRG (synergin gamma)
Description:
Plays a role in endocytosis and/or membrane trafficking at the trans-Golgi network (TGN). May act by linking the adapter protein complex AP-1 to other proteins (Probable). Component of clathrin-coated vesicles. Component of the aftiphilin/p200/gamma-synergin complex, which plays roles in AP1G1/AP-1-mediated protein trafficking including the trafficking of transferrin from early to recycling endosomes, and the membrane trafficking of furin and the lysosomal enzyme cathepsin D between the trans-Golgi network (TGN) and endosomes.
Synonyms: AP1GBP1; SYNG; MGC104959
Tractability: Antibody: UniProt places it where antibodies can reach, with medium confidence. PROTAC: ubiquitination databases record sites on it; its protein half-life has been measured.
Gene: Protein-coding gene on chromosome 17 (37,514,807 to 37,609,472, reverse strand). Ensembl gene ENSG00000275066.
Subcellular location: Cytoplasm; Golgi apparatus, trans-Golgi network membrane; Cytoplasm, perinuclear region; Cytoplasmic vesicle, clathrin-coated vesicle
Subcellular location (Human Protein Atlas): Cytosol
Gene Ontology:
Molecular function: protein binding
Biological process: intracellular protein transport
Cellular component: AP-1 adaptor complex; clathrin coat of trans-Golgi network vesicle; cytoplasm; Golgi apparatus; clathrin-coated vesicle; perinuclear region of cytoplasm
Genetic constraint (gnomAD): Loss-of-function variants: 35 observed, 122.14 expected, observed/expected ratio (o/e) 0.29, 90% interval 0.22 to 0.38. The upper end of that interval is the gene's LOEUF score, 0.38, which puts it in group 1 of 6, group 1 being the genes least tolerant of losing a copy. Missense variants: 1,277 observed, 1,570 expected, observed/expected ratio (o/e) 0.81, 90% interval 0.78 to 0.85. Synonymous variants: 520 observed, 564.66 expected, observed/expected ratio (o/e) 0.92, 90% interval 0.86 to 0.99.
Homologues: Orthologues: chimpanzee SYNRG (98% identical), macaque SYNRG (96% identical), dog SYNRG (92% identical), pig SYNRG (91% identical), rabbit SYNRG (91% identical), guinea pig SYNRG (82% identical), rat AC105531.1 (81% identical), mouse Synrg (81% identical), zebrafish synrg (58% identical), tropical clawed frog synrg (50% identical), Caenorhabditis elegans R10E11.6 (10% identical).
Diseases named in the same sentence as SYNRG in open-access papers:
SYNRG is named in the same sentence as 5 diseases in open-access papers, as found by Europe PMC text mining. Sharing a sentence is not in itself a finding about the gene and the disease. The quoted sentences say what the papers report.
bipolar disorder (1 paper, 2023). A disorder of the brain that causes unusual shifts in mood, energy, activity levels and the ability to carry out day-to-day tasks. "We also found associations between rare PTV/missense variants in C17orf78 with elevated cystatin C (ß=0.51, 95% CI 0.23 to 0.80, p=3×10−4) and SYNRG with increased risk of bipolar disorder (OR=27.45, 95% CI 3.03 to 248.61, p=8×10−4)." (PMID 36109160, 2023).
Cognitive impairment (1 paper, 2021). Abnormal cognition is characterized by deficits in thinking, reasoning, or remembering. "It has been reported in the literature that SYNRG gene mutations appear in the 17q12 microdeletion syndrome, which is related to cognitive impairment and abnormal brain structure." (PMID 33953791, 2021).
epilepsy (1 paper, 2021). A brain disorder characterized by episodes of abnormally increased neuronal discharge resulting in transient episodes of sensory or motor neurological dysfunction, or psychic dysfunction. "We could also hypothesize that SYNRG, a gene involved in Golgi trafficking and, in particular, in inwardly rectifying K+ channels (e.g., Kir4.1) export, may concur with ASD, and even be associated with epilepsy." (PMID 34828266, 2021).
generalized epilepsy (1 paper, 2014). Epilepsy that is characterized by generalized seizure types and may have typical interictal and/or ictal EEG findings that accompany generalized seizure types (for example generalized spike-wave). "We also consider generalized epilepsy (151 cases), identifying a single locus within SYNRG (top SNP rs116499908, P = 3.3 × 10−8; inflation factor 1.01)." (PMID 25063994, 2014).
SYNRG also shares sentences with these, for which no sentence is quoted: tumor (1 paper).